CNTNAP2 (contactin associated protein 2)
Diseases named in the same sentence as CNTNAP2 in open-access papers (continued):
Sharing a sentence is not in itself a finding about the gene and the disease.
neurodevelopmental disorder (47 papers, 2010 to 2026). A behavioral and cognitive disorder with onset during the developmental period that involves impaired or aberrant development of intellectual, motor, or social functions. "CNTNAP2 belongs to a group of genes associated with human diseases and primarily participates in cell proliferation, adhesion, and various neurodevelopmental disorders." (PMID 37783723, 2023). "Over the last decade, a large variety of alterations of the Contactin Associated Protein 2 (CNTNAP2) gene, encoding Caspr2, have been identified in several neuronal disorders, including neurodevelopmental disorders and peripheral neuropathies." (PMID 36793543, 2023). "There is also a strong body of literature linking mutations in CNTNAP2 to neurodevelopmental disorders." (PMID 36340692, 2022). "CNTNAP2 was associated with neurodevelopmental disorders including language deficits and variation in language development in the general population." (PMID 34539327, 2021). "The findings from this study lead to interesting questions regarding the development of novel treatments for neurodevelopmental disorders, such as CNTNAP2-associated ASD." (PMID 34471112, 2021). "Among these, CNTNAP2 has also been suggested to be associated with neurodevelopmental disorders affecting language." (PMID 21445258, 2011). "In this study, we tested whether loss of the neurodevelopmental disorder risk gene Cntnap2 altered striatal physiology or striatal-dependent behaviors." (PMID 40689867, 2025). "Notably, the mRNA levels of ASD‐related risk genes like NLGN1, SHANK2, SHANK3, and CNTNAP2 are influenced by the prenatal suppression of histone deacetylase family, which are linked to neurodevelopmental disorders." (PMID 37807632, 2023). "An environmental model of neurodevelopmental disorders in which mice were exposed to maternal immune activation (MIA) during embryogenesis has been compared with mouse models that were genetically deficient for Cntnap2, Fmr1, or Shank3." (PMID 34065644, 2021). "The CNTNAP2 gene has been implicated in several neurodevelopmental disorders." (PMID 31446765, 2019). "To explore this issue and its underlying mechanisms, we examined the impact of DLaN on the Cntnap2 KO model of neurodevelopmental disorders." (PMID 41408339, 2025). "The changes in the morphology of the CC and ACa in HET and KO mice during development are interesting with regard to the neurodevelopmental disorders in which CNTNAP2 alterations have been identified, notably ASD." (PMID 36793543, 2023). "These terminal events impact IGF1R, CNTNAP2, and DPP6, shown to be strongly associated with neurodevelopmental disorders." (PMID 31475484, 2019). "Therefore, our study raises the need to evaluate the impact of Cntnap2 heterozygosity on the functions of Caspr2 in these processes as well, to further assess the possible consequences of CNTNAP2 alterations in neurodevelopmental disorders." (PMID 36793543, 2023). "It would be interesting to test whether the manipulation of Glu or GABA actions using their receptor agonists or antagonists can affect mice behavior or cognitive ability in Cntnap2−/− mice as shown in other mouse models of neurodevelopmental disorders." (PMID 35183218, 2022). "Interestingly, they also report hypoactivity in the active phase in three other mouse models of neurodevelopmental disorders: Cntnap2−/−, Pcdh10+/−, and Fmr1 KO mice." (PMID 33396736, 2020). "Numerous genetic, neurobiological, imaging and mouse model studies have amply clarified that CNTNAP2 plays a crucial role in ASD and other related neurodevelopmental disorders." (PMID 24147096, 2013).
neurodevelopmental disorder (continued). "Other large genes with CNVs in human disorders were not expressed in the cell types used here, such as CNTNAP2, in which intragenic CNVs are found in several neurodevelopmental disorders." (PMID 25373142, 2015).
tumor (35 papers, 2009 to 2026). "The CNTNAP2 gene was identified as a fragile site, and although fragile sites are not traditional mutational targets in cancer, they do exhibit loss of expression in multiple tumor types, suggesting that they may also function as tumor suppressors." (PMID 41516419, 2026). "As both CNTNAP2 and PTPRD analyses predated the updated WHO diffuse glioma classification, we analyzed these further in the TCGA cohort with updated tumor classification based on IDH mutation and 1p19q co-deletion." (PMID 35982066, 2022). "To further study the clinical significance of PTPRD and CNTNAP2 in diffuse gliomas with the current WHO tumor classification, we analyzed TCGA diffuse glioma data for chromosomal rearrangements, CNAs, DNA methylation, and RNA expression levels of these genes." (PMID 35982066, 2022). "In the current study, the mRNA level of CNTNAP2 was 5 times lower in unfavourables versus favourable tumours." (PMID 19686582, 2009). "We detected the germline variants of RECQL4, CNTNAP2, and PRDM2, which are tumor suppressor genes." (PMID 36975488, 2023). "As CNTNAP2 gene is located in a CFS-site 7q35-36 it is not unlikely that the inactivation seen in unfavourable NB tumours is caused by entire or partial gene deletions at DNA level." (PMID 19686582, 2009). "Although elevated CNTNAP2 levels were predictive of a more unfavorable prognosis in univariate Cox regression models, disease-specific survival rates were not significantly improved by including the protein in a model containing lymph node status and tumor size." (PMID 24885002, 2014). "However, copy number analysis of more than 300 SNP's covering CNTNAP2 showed that both alleles were retained in the genome in the six analysed tumours, and gene deletions are not likely to be the cause of the low expression seen in unfavourable tumours." (PMID 19686582, 2009). "Thus, the low expression of CNTNAP2 seen in these tumours does not seem to be caused by large genomic deletions, but an inactivation may still be caused by other mutational events." (PMID 19686582, 2009). "The three transcripts, CACNA2D3, CNTNAP2 and TFAP2B, showed a 4–5 times lower expression in unfavourable tumour types." (PMID 19686582, 2009). "Interestingly, all these three genes additionally exert their function as tumor suppressor genes (AHRR, GFI1, CNTNAP2)." (PMID 27493699, 2015). "Furthermore, outcome prediction was not improved using a predictive model for DSS including CNTNAP2 expression, lymph node status, and tumor size (C-index = 0.949) compared with a model containing lymph node status and tumor size (C-index = 0.941)." (PMID 24885002, 2014). "However, the analyses of POU4F2 and CNTNAP2 showed no genetic alterations that could explain a lower expression in unfavourable NB tumours." (PMID 19686582, 2009).
neurological disorders (33 papers, 2013 to 2026). "Anti-contactin-associated protein-2(CASPR2) antibody associated neurological disease is rare in adults, which is rarer in children." (PMID 39183357, 2024). "The contactin-associated protein-like 2 (CNTNAP2) gene, one of the neurexin family genes, appears to be one of the major susceptibility genes for various neurological disorders including ASD." (PMID 31438473, 2019). "Genetic alterations on the CNTNAP2 gene, such as copy number variations, genomic inversion, single nucleotide polymorphisms, and complete loss of CNTNAP2 gene are known to be associated with several neurological disorders." (PMID 36253443, 2023). "Molecular mimicry is implicated in neurological disorders associated with anti-CNTNAP2 antibodies." (PMID 24466509, 2014). "This review synthesizes current knowledge of CNTNAP2 biology, highlighting isoform- and context-specific mechanisms and outlining key unanswered questions relevant to both neurological disease and cancer." (PMID 42110583, 2026). "In addition, CNTNAP2 mediated signaling is generally considered to play a role in neurological disorders due to its critical role in neurodevelopment, neurotransmission, and synaptic plasticity." (PMID 35628852, 2022).
cancer (22 papers, 2013 to 2026). A tumor composed of atypical neoplastic, often pleomorphic cells that invade other tissues. "The top 10 frequently affected cancer-associated genes are HIRA (OG), CSMD1 (TS), CDH13 (TS), PRRX1 (OG), FHIT (TS), MGAM (OG), TBL1XR1 (OG), RHOA (OG), FGF14 (TS), and CNTNAP2 (TS)." (PMID 35013466, 2022). "Similarly, we identified 57 potential TSGs, of which at least 13 have been implicated in cancer, including HOXB13, ZNF350, ZNF331, CNTNAP2, NEFH, and ABR with reduced expression due to hypermethylation or loss." (PMID 37245006, 2023). "The direction of the altered expression of LIFR, ARHGAP24, and CNTNAP2 varied in each cancer type." (PMID 33463006, 2021). "These genes were presumably involved in cancer (SMG6, HCK), cellular growth (CPVL), reproduction (ADGB, CRISP1, CTTNBP2NL, WDR78), and nervous system (AUTS2, CNTNAP2, CPVL, SRGAP2)." (PMID 40149444, 2025). "Integration events occurring in single samples were observed in the following cancer-driver genes: TERT, KMT2B (MLL4), RIMS1, FN1, RBFOX1, CNTNAP2 and THRB7,11,12,14,27,28." (PMID 37400627, 2023). "The results showed that the expression of ANK3 (in the proteoglycans in cancer pathway), CDH3, and CNTNAP2 (in the cell adhesion molecule pathway) was downregulated." (PMID 35745623, 2022). "We identified 35 genes that were more frequently altered in HS/CB tumors versus corresponding TCGA cohorts; of which, 8 genes (PREX2, BIRC6, CNTNAP2, PTPRB, GRM3, ANKRD11, BRCA2, and TET3) are listed on the OncoKB Cancer Genes catalogue." (PMID 34446728, 2021).
psychiatric disorder (11 papers, 2018 to 2026). A disorder characterized by behavioral and/or psychological abnormalities, often accompanied by physical symptoms. "We identified 7 genes (Cap2, Shc3, Lrrc7, Rims2, Cntnap2, Tcf20, and Trank1) associated with neurodevelopmental and psychiatric disorders that feature social impairments." (PMID 38263132, 2024). "To better understand the involvement of CNTNAP2 in risk of mental illness, we performed several genetic analyses using a series of large publicly available or in-house datasets, comprising many thousands of patients and controls." (PMID 30586385, 2018). "Other studies considered genetic sequence variations that are common in the general population, and suggested that two such sequence variations in CNTNAP2 predispose to psychiatric diseases by influencing the functionality and connectivity of the brain." (PMID 30586385, 2018). "In conclusion, our results converge to show a limited or likely neutral role of CNTNAP2 in the susceptibility of psychiatric disorders." (PMID 30586385, 2018). "Overview of studies implicating common alleles, structural variants or rare variants of CNTNAP2 in psychiatric disorders." (PMID 30586385, 2018). "Gene-based tests for association of CNTNAP2 across seven psychiatric disorders using GWAS summary statistics of the PGC data sets." (PMID 30586385, 2018). "Next, we explored the contribution of common variants across CNTNAP2 by performing a gene-based association study in MAGMA using GWAS summary statistics from PGC data of seven psychiatric disorders in European populations." (PMID 30586385, 2018). "We aimed to comprehensively examine evidence for the role of CNTNAP2 in susceptibility to psychiatric disorders, by the analysis of multiple classes of genetic variation in large genomic datasets." (PMID 30586385, 2018). "Common SNPs in CNTNAP2 previously reported to be associated in psychiatric diseases, and their evidence for association in PGC datasets." (PMID 30586385, 2018). "Here we performed analyses using large publicly available datasets investigating a range of mutational mechanisms which impact variability of CNTNAP2 across several psychiatric disorders." (PMID 30586385, 2018). "This suggests a possible role for dendritic development impairment in mental disorders with CNTNAP2 pathology." (PMID 36430976, 2022). "Although not segregating closely with BD, we identified CNVs affecting intronic regions of candidate genes previously implicated in psychiatric disorders (i.e., NLGN1, CNTNAP2, KCNB2 and CNTN5), each in different families." (PMID 29531218, 2018). "Furthermore, examination of de novo variants in combined psychiatric sequencing projects of over 15,500 trios suggest that de novo variants in CNTNAP2 do not increase risk for psychiatric disorders." (PMID 30586385, 2018).
peripheral neuropathy (6 papers, 2015 to 2024). A disorder affecting the peripheral nervous system. "Based on the genotype-phenotype correlations of these three CNVs, we consider LAMA2 to be a new potential target gene for peripheral neuropathy, whereas CNTNAP2 and SEMA5A remain potentially pathogenic." (PMID 25648254, 2015).
CNTNAP2 also shares sentences with these, for which no sentence is quoted: Encephalopathy (18 papers); psychosis (14); insomnia (11); Seizure (11); cerebellar ataxia (10); amnesia (9); movement disorder (9); sleep disorder (9); dysautonomia (8); myasthenia gravis (8); Parkinsonism (7); memory impairment (6); Stroke (6); Chorea (5); dementia (5); Hyponatremia (5); diabetes (4); infection (4); malignant thymoma (4); multiple sclerosis (4); Myokymia (4); cerebellar degeneration (3); chronic inflammatory demyelinating polyneuropathy (3); cognitive disorder (3); Epileptic encephalopathy (3); episodic ataxia (3); Guillain-Barre syndrome (3); Hyperhidrosis (3); Hypertension (3); Pitt-Hopkins syndrome (3).
A further 141 diseases each share a sentence with CNTNAP2 in 3 papers or fewer.